ARID1A (AT-rich interaction domain 1A)
Diseases named in the same sentence as ARID1A in open-access papers (continued):
Sharing a sentence is not in itself a finding about the gene and the disease.
hepatocellular carcinoma (74 papers, 2013 to 2026). A malignant tumor that arises from hepatocytes. "Mutations in the SWI/SNF pathway were more likely to happen late in hepatocellular carcinoma, with ARID1A being one of the most frequently mutated genes in this pathway." (PMID 39868264, 2025). "Another study in a hepatocellular carcinoma model investigated metabolic perturbations in tumor cells with mutations in the ARID1A (BAF250) subunit of SWI/SNF." (PMID 38666605, 2024). "The ARID1A mutation was more frequent in cholangiocarcinoma than mixed-tumor cholangio/hepatocellular carcinoma and was associated with ductal plate malformation patterns, which are developmental anomalies that originate from insults to the ductal plate." (PMID 38203635, 2023). "In earlier studies, numerous mutated genes in hepatocellular cancer have been identified, with ARID1A being the most contentious." (PMID 35028302, 2022). "In hepatocellular carcinoma, ARID1A deficiency promotes angiopoietin-2-induced angiogenesis that correlates with the cancer progression and aggressiveness." (PMID 35069887, 2022). "GSEA searches for physiological processes that are activated differentially in hepatocellular carcinoma by identifying ARID1A-associated signal pathways." (PMID 35028302, 2022). "Recently, the role of USP9X in ARID1A-deficient hepatocellular carcinoma was reported to involve a synthetic lethal interaction between ARID1A deficiency and inactivation of adenosine 5′-monophosphate-activated protein kinase (AMPK)." (PMID 36123603, 2022). "Meantime, loss of ARID1A was found to be associated with the poor prognosis of a variety of cancers including hepatocellular carcinoma (HCC) and endometrial carcinoma (EC)." (PMID 34715776, 2021). "For example, loss of function mutations in ARID1A have been reported in >16% of human hepatocellular carcinoma." (PMID 33732709, 2021). "For example, Zhu and colleagues demonstrated in murine models of hepatocellular carcinomas (HCCs) that sustained Arid1a expression was pro-tumorigenic, while loss of Arid1a was deleterious, during primary tumor formation." (PMID 32967217, 2020). "Mutation of ARID1B is rarer than that of ARID1A in human cancer, but has been found in hepatocellular carcinoma and neuroblastoma." (PMID 29890703, 2018). "In liver cancer, ARID1A mutations were observed in 10–16.8 % of the studied tumors and in 13 % of hepatitis B virus-associated hepatocellular carcinomas." (PMID 25975202, 2015). "Recently, several groups, including ours, detected ARID1A mutations in 10–15% of hepatocellular carcinoma (HCC)." (PMID 26569409, 2015). "The ARID1A gene is the most commonly mutated gene in 10%-15% of hepatocellular carcinomas (HCCs)." (PMID 39609317, 2024). "ARID1A mutations are detected with high frequency in tumor samples of entities including endometrioid and clear-cell ovarian cancer (>40%), gastric cancer, bladder cancer, hepatocellular cancer, colorectal cancer and melanoma (11.5%)." (PMID 35565222, 2022). "Indeed, a whole-exome sequencing analysis detected both Kit and Arid1a mutations in 69 hepatocellular carcinoma samples." (PMID 33327223, 2020). "The current study aims to explored the immune-modulating role of ARID1A deficiency in Hepatitis B virus (HBV) related hepatocellular carcinoma (HBV-HCC) and its potential immunotherapeutic implications." (PMID 38166741, 2024). "Hepatocellular Carcinoma (HCC): ARID1A is one of the most frequently mutated genes in hepatocellular carcinoma, with mutations occurring in 10% to 17% of cases." (PMID 38893181, 2024). "Additionally, the overexpression of ARID1A has been linked to hepatocellular carcinoma (HCC)." (PMID 38473997, 2024).
hepatocellular carcinoma (continued). "ARID1A mutations are observed in 10–16.8% of hepatocellular carcinoma (HCC), and 13% of hepatitis-B-virus-associated HCC." (PMID 38275587, 2023). "ARID1A expression seems to have a significant role in overall survival in MultiCox and UniCox analyses, suggesting that it may be utilized as a therapeutically useful self-governing risk indicator for hepatocellular carcinoma." (PMID 35028302, 2022). "ARID1A also exhibits tumour‐suppressive functions in hepatocellular carcinoma (HCC) by inhibiting interactions with the long non‐coding RNA (lncRNA) MVIH through the ARID domain or the C‐terminal ARID1A protein‐binding domain." (PMID 38041544, 2023). "A double functional role for ARID1A in tumorigenesis has been described in hepatocellular carcinoma (HCC)." (PMID 36890819, 2023). "The iCCA is considered the second most commonly diagnosed primary hepatic malignancy after hepatocellular carcinoma (HCC), presenting several genetic alterations, such as FGFR and IDH1/2 fusion, as well as ARID1A and BRAF mutations." (PMID 37958547, 2023). "While a relationship between ARID1A promoter hypermethylation and disease progression had been shown before for squamous cell carcinoma, the situation was unclear for hepatocellular carcinoma (HCC)." (PMID 36139547, 2022). "ARID1A and LRP1B are mutated in 10% and 6.4% of human hepatocellular carcinomas within five studies compiled in cBioPortal." (PMID 35557512, 2022). "ARID1A encodes a subunit of SWI/SNF, and its deletion in hepatocellular carcinoma induces conversion of the A/B region, remodeling of TADs, and a reduction in chromatin loops." (PMID 35965507, 2022). "Then, using hepatoma cell lines, we investigated the connection between ARID1A expression and immune infiltration." (PMID 35028302, 2022). "Briefly, ARID1A is required for tumor initiation in the early stages of hepatocellular carcinoma, while in later stages, such as in established tumors, ARID1A inhibits tumors progression and metastasis." (PMID 36361605, 2022). "Patients with elevated ARID1A expression in their hepatocellular carcinoma tissues had a short prognosis." (PMID 35028302, 2022). "Our previous work demonstrated that ARID1A was mutated in 13% of hepatitis B virus (HBV) infection-associated hepatocellular carcinoma (HCC) specimens, and ARID1A mutations were considered as a crucial event in liver cancer metastasis." (PMID 34689165, 2021). "The author showed that ARID1A was required for initial tumor development and to be inhibitory of hepatocellular carcinoma metastatic potential, indicating the role of ARID1A in oncogenesis was dependent on tissue context." (PMID 34249744, 2021). "ARID1A is a commonly mutated tumor suppressor gene found in all human cancer types, but its clinical significance, oncogenic functions, and relevant mechanisms in hepatocellular carcinoma (HCC) are not well understood." (PMID 33771191, 2021). "In conclusion, our results have shown that ARID1A is frequently downregulated in hepatocellular carcinoma and is related to the aggressive phenotype of HCCs." (PMID 25975202, 2015). "Since epithelial-mesenchymal transition (EMT) is one of the crucial events regulating hepatocellular carcinoma, prostate cancer invasion and metastasis, we checked EMT associated proteins in ARID1A knockdown and overexpression cells." (PMID 25975202, 2015). "In hepatocellular carcinoma, ARID1A demonstrated a higher expression in primary tumors than in metastatic tumors, which suggests that ARID1A expression may be decreased after the initiation of oncogenesis." (PMID 39796161, 2025). "ARID1A has context-dependent roles in mouse models of hepatocellular carcinoma." (PMID 38275587, 2023). "From a bioinformatics perspective, our results suggest that ARID1A is already highly expressed in hepatocellular carcinoma and may play a role in tumor start." (PMID 35028302, 2022).
hepatocellular carcinoma (continued). "ARID1A, encoding a subunit of chromatin remodeling SWI/SNF complexes, has recently been considered as a new type of tumor suppressor gene for its somatic mutations frequently found in various human tumors, including hepatocellular carcinoma (HCC)." (PMID 26569409, 2015). "Consistent with the pro-tumor functions of ARID1A under certain contexts, such as hepatocellular carcinoma (HCC), the tumors have higher expression levels of ARID1A than adjacent normal tissues." (PMID 36980292, 2023). "Suppressing the NF2 gene in the ARID1A mutant background gave iPSCs a growth advantage and, although direct interaction of ARID1A and NF2 is not known, both proteins regulate pathways inhibiting oncogenic YAP/TAZ genes, and their double mutation causes hepatocellular carcinoma in mice." (PMID 37028423, 2023). "Silencing Arid1a gene in murine hepatocellular carcinoma (HCC) cells increases blood vessel density in the tumor by inducing expression of Ang2, a gene encoding angiogenic factor angiopoietin 2 (ANG2)." (PMID 38017409, 2023). "In human hepatocellular carcinoma (HCC), the most common primary liver cancer, ARID1A is the chromatin modifier gene the most frequently inactivated (>13% of HCCs)." (PMID 33084574, 2020). "Interestingly and consistently with our gene expression data, TERF2 and ARID1A, which are two of the most frequently altered genes in hepatocellular carcinoma (HCC), were among these peptides." (PMID 31783479, 2019). "Similarly, deletion of Arid1a from otherwise wild-type mice protects against DEN (diethylnitrosamine)-induced hepatocellular carcinoma (HCC), while overexpression of Arid1a accelerated tumor initiation." (PMID 31217031, 2019). "In the current study, we performed a comprehensive analysis using bioinformatics approaches and pre-clinical experiments to evaluate the ARID1A regulatory role on the biological behavior, and immune landscape of Hepatitis B virus (HBV) related hepatocellular carcinoma (HBV-HCC)." (PMID 38166741, 2024). "However, deficiency of Arid1a in mouse HCC (hepatocellular carcinoma) cells did not alter several of the angiogenesis-related genes, including Vegfa, Fgf2, Egfl7, Sdf1, Hif1a, Hif2a and Ang1." (PMID 38017409, 2023). "In hepatocellular carcinoma (HCC), subunit‐specific perturbations demonstrate oncogenic consequences: ARID1A (BAF250a) inactivation promotes metastatic progression via steatosis‐associated genomic instability." (PMID 41578412, 2026). "In some patients with hepatocellular carcinoma, ARID1A was strongly expressed in primary tumors but not in metastatic lesions, suggesting that ARID1A may be lost after initiation." (PMID 36844227, 2023). "Interestingly, research has shown that innate immune cells like macrophages and neutrophils can infiltrate the liver and contribute to hepatocellular carcinoma development in the absence of ARID1A in mice." (PMID 38041544, 2023). "Its oncogenic properties are not well understood and are seemingly complex; ARID1A appears to increase oxidative stress, such as by increasing CYP450 in the liver in hepatocellular carcinoma (HCC)." (PMID 35626165, 2022). "In hepatocellular carcinoma (HCC), ARID1A is often inactivated by genomic deletion or non-sense mutations." (PMID 38727317, 2024). "Lack of ARID1A markedly reduces BRG1–RAD21 coupling, leading to increased chromatin accessibility and promoting hepatocellular carcinoma metastasis." (PMID 35965507, 2022).
endometrioid carcinomas (66 papers, 2011 to 2026). "These cancers include aggressive subtypes, such as high-grade endometrioid carcinomas, serous carcinomas, and clear cell carcinomas, where ARID1A mutations contribute significantly to tumor progression, genomic instability, and treatment resistance." (PMID 40072110, 2025). "In high-grade endometrioid carcinomas, ARID1A mutations are present in over 40% of cases, while in low-grade endometrioid carcinomas, they are observed in only 25% of cases." (PMID 38893147, 2024). "The ARID1A gene is commonly mutated or lost in ovarian clear-cell and endometrioid carcinomas and pre-cancer lesions." (PMID 39766121, 2024). "The ARID1A-encoded protein and BAF250a expression genes are most associated with clear cell and endometrioid carcinomas as well as benign endometriosis." (PMID 39202622, 2024). "Endometrial Cancer: The rate of ARID1A mutation in low-grade endometrioid adenocarcinomas is 47%, while in high-grade endometrioid adenocarcinomas, serous adenocarcinomas, and carcinosarcomas, it is 60%, 11%, and 24%, respectively." (PMID 38893181, 2024). "The significance of Arid1a mutations in gynaecological cancers was discovered in 2010 when mutations in Arid1a were found in almost half of ovarian clear cell and endometrioid carcinomas." (PMID 38275587, 2023). "The finding of ARID1A loss in complex atypical hyperplasia of endometrial curettage is highly predictive of endometrioid adenocarcinoma at surgery." (PMID 38275587, 2023). "The mutations of PIK3CA and CTNNB1 genes, as well as the alteration of the SWI/SNF complex, that was documented in our case by the loss of ARID1A expression, are among the most common and earliest genetic abnormalities detected in endometrioid carcinoma." (PMID 34342838, 2022). "In endometrioid carcinomas, ARID1A mutations often co-occurred with PTEN mutations, and concurrent loss of those tumor suppressors has been shown to have synergistic effects on tumorigenesis." (PMID 33947352, 2021). "For example, AT-rich interactive domain-containing protein 1A (ARID1A), which is frequently mutated in ovarian clear cell and endometrioid carcinomas, was shown to maintain the glutathione homeostasis by enhancing SLC7A11 transcription." (PMID 33401771, 2021). "Complete loss of ARID1A expression or clonal ARID1A mutation is rare in atypical endometrial hyperplasia while up to one-third of endometrioid carcinomas lose ARID1A expression or harbor somatic ARID1A mutations." (PMID 32483112, 2020). "Some reports described mutations of the ARID1A gene in 30% of women with endometrioid carcinoma derived from ovarian endometrioma." (PMID 33308243, 2020). "TFF3 expression, ARID1A loss and beta-catenin expression had 100% specificity in diagnosing grade 3 endometrioid carcinoma, but relatively low sensitivity at 37%, 33%, and 7%, respectively." (PMID 30550483, 2019). "Low-grade endometrioid carcinomas, however, are similar to clear cell adenocarcinomas in their association with endometriosis, expression of ARID1A mutations, and activation of the PI3K-Akt pathway." (PMID 27231561, 2015). "Loss of ARID1A has also been identified in endometrial hyperplasia with atypia, the precursor lesion of endometrioid carcinoma, and appears to be an early event in its pathogenesis." (PMID 27231561, 2015). "Endometrioid carcinoma patients had a high prevalence of concurrent mutations of ARID1A, PTEN and PIK3CA and could therefore be easily identifiable candidates for a combination of inhibitors of PARP and the MTOR pathway." (PMID 33947352, 2021). "In this study, we investigated the role that ARID1A inactivating mutations in the endometrium might play in the development and progression of endometrioid carcinoma." (PMID 32483112, 2020). "Aberrations in other functional pathways resulting from ARID1A inactivating mutations may well account for the observed aggressive phenotype in the iPAD mouse model and human endometrioid carcinomas." (PMID 32483112, 2020).
endometrioid carcinomas (continued). "Moreover, loss of ARID1A expression is known to occur in approximately 40% of low-grade endometrioid carcinomas." (PMID 27322430, 2016). "Moreover, endometrioid carcinomas exhibit the loss of ARID1A with enhanced VEGF expression." (PMID 35069887, 2022). "During the development of AEH, the PTEN gene undergoes somatic mutations and then mutations in the ARID1A gene and inactivation of TGF‐β are involved in the ultimate progression into invasive endometrioid carcinoma." (PMID 40177982, 2025). "ARID1A (also known as BAF250A), an important component of the SWI/SNF nucleosome remodeling complex, is also one of the most frequently mutated genes in endometrioid carcinoma." (PMID 38539494, 2024). "In a clear cell or endometrioid carcinoma histotype, the AT-rich interactive domain-containing protein 1A (ARID1A), a tumour suppressor gene involved in chromatin remodelling, is often inactivated." (PMID 39579091, 2024). "To further strengthen this finding, we obtained uterine endometrioid carcinoma tissues and segregated them into ARID1A-high and ARID1A-low groups by immunoreactivity." (PMID 38071325, 2023). "Following exclusion of ARID1A oncogenic variants, oncogenic HRR gene variants were detected in 14.3% (3/21) of serous and 38% (8/21) of endometrioid carcinomas." (PMID 36922497, 2023). "Clear cell carcinoma is characterized by ARID1A, PIK3CA, TERT promoter mutations, and endometrioid carcinoma is characterized by PTEN, PIK3CA, ARID1A, and CTNNB1 mutations." (PMID 31130643, 2019). "Additional studies will have to be conducted to evaluate the association between ß-Catenin and the chromatin remodelling gene ARID1A in uterine endometrioid carcinoma further." (PMID 29451900, 2018). "Immunohistochemistry assays demonstrated that a substantial proportion of uterine endometrioid carcinomas, uterine clear-cell carcinomas, uterine serous carcinomas, and uterine carcinosarcomas also have loss of ARID1A protein (BAF250a)." (PMID 25975202, 2015). "ARID1A, a tumor suppressor gene encoding BAF250, a protein participating in chromatin remodeling, is frequently mutated in endometrium-related malignancies, including ovarian or uterine clear cell carcinoma (CCC) and endometrioid carcinoma (EMCA)." (PMID 38071325, 2023). "Classically, uterine endometrioid adenocarcinomas, which are most associated with ARID1A mutations, are often indolent, low-grade tumors not generally associated with metastatic risk." (PMID 34941867, 2021). "It is well known that ARID1A mutations are frequently detected in ovarian clear cell and endometrioid carcinomas but not in high-grade serous ovarian carcinomas." (PMID 32868822, 2020). "For endometrioid carcinoma, ER and progesterone (PR) receptors were observed in 34 and 21% of cases, respectively, and one case of EC with mucinous features had a loss of MSH6 and ARID1A in tumor cells with a positive stain in stromal tissue and lymphocytes." (PMID 32677969, 2020). "IHC staining of 6 EC cases (5 endometrioid carcinoma and 1 carcinosarcoma) with DICER1 hotspot mutations only identified ARID1A loss in one endometrioid carcinoma case, but neither SMARCA4 nor ARID1B was lost in any of the 6 cases." (PMID 33052929, 2020). "Another model of endometrioid carcinoma in mice utilized a double conditional knockout of Pten and Arid1a and intrabursal AdCre injection to show a progression of ovarian surface epithelium hyperplasia, endometrioid carcinoma, and finally poorly differentiated carcinoma." (PMID 30087267, 2018).